MMP10 (matrix metallopeptidase 10)
Diseases named in the same sentence as MMP10 in open-access papers (continued):
Sharing a sentence is not in itself a finding about the gene and the disease.
tumor (continued). "Depletion of Mmp10 in the shG9a background significantly reduced tumor burden following intravenous transplantation (38.3 vs. 3.9%, P < 0.0001, t test), implying that Mmp10 functions in the TPC phenotype." (PMID 30455465, 2018). "We depleted Mmp10 from cell lines derived from shG9a tumors with shRNA hairpins and compared their tumor-forming efficiency with shGFP controls." (PMID 30455465, 2018). "Since G-CSF and MMP10, which are known to promote tumor growth, levels were affected by FRG1, we looked for FRG1 expression in tumor tissues." (PMID 28947680, 2017). "In this study, we observed that the levels of MMP-1, MMP-2, and MMP-10 significantly increased in co-cultures of tumor cells/monocytes, and we have previously shown that this correlates with increased collagen degradation." (PMID 28337194, 2017). "The tumor derived from MMP10-overexpressed RMG1 cells showed faster growth than that of the tumor derived from mock-transfected RMG1 cells." (PMID 27072580, 2016). "Since CSCs/CICs were defined by their higher tumor-initiating ability, we investigated the tumor-initiating abilities of MMP10-overexpressed cells and MMP10 knockdown cells using immune-deficient nude mice." (PMID 27072580, 2016). "MMP10-overexpressed RMG1 cells initiated tumor formation in 6 of 6 mice, 6 of 6 mice and 4 of 6 mice injected with 103 cells, 102 cells and 101 cells, respectively." (PMID 27072580, 2016). "MMP-10 is highly expressed in SCC stromal cells and is up-regulated by tumor-associated cytokines including TGF-β and TNF-α." (PMID 27271600, 2016). "The overall average mRNA expression levels of Mmp3, Mmp10, and Mmp13 were higher in tumor than that in normal tissues (left)." (PMID 25742789, 2015). "MMP-10 is considered to be the most important factor in human tumor cells that can activate other MMP (such as MMP-1) precursors." (PMID 25120597, 2014). "MMP-10 is considered an important factor in the activation of other MMP (such as MMP-1) precursors in human tumor cells." (PMID 25120597, 2014). "MMP-10, one of the lesser studied MMPs, is limited to epithelial cells and can facilitate tumor cell invasion by targeting collagen, elastin and laminin." (PMID 24885595, 2014). "In this study, we monitored MMP-10 expression in cohorts of human tumor tissues, and investigated the mechanistic role of this MMP using a panel of in vitro and in vivo studies." (PMID 24885595, 2014). "The in vivo observations corroborate the in vitro findings and confirm a role for MMP-10 in the provision of a pro-tumor growth environment through an influence on angiogenesis and apoptosis." (PMID 24885595, 2014). "Analysis of gene expression data from human cancers reveals a strong positive correlation between tumor Mmp10 expression and metastatic behavior in many human tumor types." (PMID 22545096, 2012). "Primary tumors derived from oncospheres exhibited slightly elevated Mmp10 staining with darker Mmp10 staining in areas where the tumor interacts with surrounding stroma." (PMID 22545096, 2012). "Mmp10 is highly induced in tumor-initiating lung bronchio-alveolar stem cells (BASCs) upon activation of oncogenic Kras." (PMID 22545096, 2012). "Analysis of expression profiling data on NSCLC revealed a significant correlation between Mmp10 expression and tumor progression, local invasiveness and distant metastasis." (PMID 22545096, 2012). "In primary oncosphere-derived tumors we observed enhanced Mmp10 and Notch4 staining at the interface between the tumor and surrounding tissue, suggesting a role for Mmp10+/Notch4+ cells in tumor invasion." (PMID 22545096, 2012). "Notch4 staining exhibited a similar pattern, indicating co-expression of Mmp10 and Notch4 in tumor cells at the interface of the tumor and surrounding stroma (upper)." (PMID 22545096, 2012). "Our current study provides compelling evidence that Mmp10 exerts its pro-tumorigenic effects, at least in part, by maintaining a population of CSCs that drive tumor initiation and metastasis." (PMID 22022614, 2011).
tumor (continued). "Matrix metalloproteinase 10 (MMP-10; stromelysin 2) is a member of a large family of structurally related matrix metalloproteinases, many of which have been implicated in tumor progression, invasion and metastasis." (PMID 22022614, 2011). "The ability of MMP-10 to promote neoplasia has been inferred to its secretion by peritumoral cells in response to the presence of signals provided by the tumor cells." (PMID 21998657, 2011). "Immunohistochemical analysis demonstrated that Mmp10 expression is elevated in urethane-induced tumors, particularly at areas of contact between the tumor and the surrounding stroma." (PMID 22022614, 2011). "An intriguing subset of genes in the cornea signature has been studied in tumor metastasis models because these genes encode proteins that regulate cell-cell or cell-matrix interactions (TWIST, MMP10, SERPINB5, THBS1, CEACAM1, C4.4A)." (PMID 16168081, 2005). "The upregulation of the serine protease inhibitor and matrix metalloproteinase genes Serpinb2 and Mmp10 in the tumor microenvironment of knockout mice suggests a tumor-suppressive function through the regulation of extracellular matrix remodeling and modulation of immune responses 58,59." (PMID 41377951, 2025). "Furthermore, Mmp10-positive TSKs correlated with G2/M clusters, suggesting that they reside in proliferative tumour areas." (PMID 39020166, 2024). "For instance, matrix metalloproteinases (MMP1, MMP3, MMP10, MMP12), while traditionally associated with promoting tumor cell invasion and metastasis, have been shown in recent studies to facilitate ferroptosis in the right context by inducing lipid peroxidation." (PMID 39372411, 2024). "Notably, we observed an influence of TIMP1, demonstrating a positive correlation with MMP8, MMP9, and MMP10 in tumor samples." (PMID 38474106, 2024). "MMP10 protein was mainly detected in the cytoplasm of tumor cells." (PMID 36650344, 2023). "We also find that MMP10 regulates tumor radiosensitivity through the DNA damage repair pathway." (PMID 36908704, 2023). "We also found that MMP10 gene mutation data in TCGA-LUAD showed a better survival level which meant MMP10 might play a role in promoting tumor progression indirectly." (PMID 36908704, 2023). "MMP-10 is upregulated in various cancers and is involved in tumor metastasis." (PMID 35216251, 2022). "Moreover, the expression of MMP-10 in RCC can be harnessed as a potential therapeutic target to inhibit RCC tumor progression." (PMID 35216251, 2022). "MMP1 and MMP10 mainly affect the migration, invasion and angiogenesis of tumour cells." (PMID 35501390, 2022). "Moreover, in animal models of induced hepatocarcinoma MMP10 KO mice developed reduced tumor vascular density, as measured by CD31 immunostainings, compared to control mice." (PMID 35884862, 2022). "For example, pre-metastatic factors such as Ang2, MMP3 and MMP10, which are upregulated in the pre-metastatic lungs by primary tumours, can disrupt the vascular integrity synergistically to facilitate the extravasation of tumour cells." (PMID 35006432, 2021). "In addition, in the case of SCC, there was a positive correlation between the MMP-10 expression and tumor grade." (PMID 34204372, 2021). "This study is the first to identify MMP10 as the main stromal protein to drive EMT in tumor cells." (PMID 33105540, 2020). "Additionally, the aPKC-ι-Par6-Rac1-Pak-Mek-Erk signaling axis drove anchorage-independent tumor growth and invasion through the induction of MMP10 expression." (PMID 32144235, 2020). "MMP10 promoted HCC by involving in tumor angiogenesis, growth, and dissemination." (PMID 31139015, 2019). "MMP-10, or stromelysin-2, is mainly found in epithelial cells and is involved in tumor cell invasion and metastasis by targeting several pro-MMPs, as well as breaking down ECM components such as collagen, gelatin, elastin, fibronectin, proteoglycans, and laminin." (PMID 31886121, 2019).
tumor (continued). "As G9a represses Mmp10 and other secreted proteases, we asked if G9a could regulate how tumor cells interact with the ECM." (PMID 30455465, 2018). "It is noted that MMP10 is essential to the tumor microenvironment." (PMID 29933410, 2018). "Nevertheless evidence likewise exists that MMP10 also displays tumor-protective capabilities." (PMID 27431388, 2016). "Taken together, our findings show that MMP-10 can play a significant role in tumor growth and progression, and that MMP-10 perturbation may represent a rational strategy for cancer treatment." (PMID 24885595, 2014). "To address whether YY1 knockdown-mediated tumor invasion is dependent on MMP10 activity, we used siRNA experiments to knockdown MMP10 expression in vitro." (PMID 24884523, 2014). "We next investigated whether MMP-10 might contribute to key tumor cell processes including migration and invasion." (PMID 24885595, 2014). "Cross reactivity between the species-specific siRNAs was not noted in vitro (data not shown), thus, we speculate that there is some positive feedback link between mouse stromal MMP-10 and HeLa tumor cell MMP-10 production." (PMID 24885595, 2014). "Our orthotopic tumor model shows Mmp10 staining in tumor cells but not tumor-associated stroma or morphologically normal lung epithelium." (PMID 22545096, 2012). "These stem-like properties require expression of Mmp10 in tumor cells but not in tumor-associated stroma." (PMID 22545096, 2012). "Tumor-associated stroma and normal lung epithelium stain negative for Mmp10, consistent with the paucity of Mmp10 expression in normal lung epithelium." (PMID 22545096, 2012). "Interestingly, tumor cells within metastatic lesions uniformly express Mmp10 and Notch4 suggesting that they are derived from, and highly enriched in, CSCs." (PMID 22545096, 2012). "This inhibitory effect is reflected in a defect in the ability of Mmp10-deficient BASCs to expand and undergo transformation in response to urethane or oncogenic Kras in vivo and in vitro, demonstrating a role for Mmp10 in the tumor-initiating activity of Kras-transformed lung stem cells." (PMID 22022614, 2011). "Thus, while many MMPs produced by the tumor microenvironment play prominent roles in the invasive and metastatic properties of lung tumor cells, our data demonstrate that Mmp10 specifically functions to support the autonomous growth of CSCs." (PMID 22022614, 2011). "Both the KrasLA2 and urethane tumor models show Mmp10 staining in tumor cells, with little to no staining in tumor associated-stroma or morphological normal lung epithelium." (PMID 22022614, 2011). "Finally, Mmp10 is elevated in many human tumor types suggesting a widespread role for Mmp10 in human malignancy." (PMID 22022614, 2011). "Similarly, the expression of matrix metallopeptidase 10 (MMP10 or Stromolysin 2), an enzyme implicated in the breakdown of extracellular matrix during tumor invasion, metastases and angiogenesis, was highly induced (11 fold) upon induction of K13 activity." (PMID 19660139, 2009). "Our research results suggest that MMP10 may play an important role in tumor radioresistance." (PMID 36908704, 2023). "In addition, AJUBA mRNA levels were significantly associated with elevated MMP10 and MMP13 expression in 179 ESCC tumor tissues (r = 0.441, P < 0.001 and r = 0.404, P < 0.001, respectively), suggesting that AJUBA promotes the expression of MMP10 and MMP13 in ESCC." (PMID 27172796, 2016). "In addition, MMP-10 and other activated MMPs may disrupt the basement membrane, providing the necessary conditions for the invasion and metastasis of tumor cells through the vasculature." (PMID 25009646, 2014). "Thus, Mmp10 mediates tumor initiation through control of tumor-initiating cell (BASC) expansion." (PMID 22545096, 2012). "However, we cannot rule out a role for Mmp10 produced by tumor-associated epithelial, stromal and/or immune cells in our orthotopic tumor studies." (PMID 22545096, 2012).
tumor (continued). "Thus, tumor cells are the major source of Mmp10 in the lungs of tumor-bearing mice." (PMID 22545096, 2012). "Interestingly, Mmp10 is highly expressed in NSCLC tumors but not tumor-associated stromal cells, whereas Mmp3 and Mmp11 are expressed predominantly in stroma." (PMID 22545096, 2012). "Our analysis revealed that TIMP1 was predominantly expressed across various cell types, particularly stromal cells, while MMP10 and F2RL2 exhibited low expression levels in both non-tumor and tumor cells." (PMID 40777024, 2025). "Specifically, L1low cells upregulate matrix metalloproteinases MMP2 and MMP10, enzymes that degrade ECM components to facilitate tumor dissemination." (PMID 40770187, 2025). "The paired sample comparison graph demonstrated that the expression levels of ILF3, MMP9, MMP10, MMP11, and MMP26 in PCa tumor tissue were elevated than adjacent non-tumor tissues (P < 0.05)." (PMID 40607407, 2025). "In HCC, MMP10 has also been reported as contributing to HCC development, participating in tumor angiogenesis, growth, and dissemination." (PMID 39756915, 2024). "Analysis of the DEGs in TCGA tumours revealed that the miR-18a/low tumours expressed high levels of EMT master regulators-ZEB1 and ZEB2 and Matrix metalloproteinases, MMP2, MMP3, MMP10, MMP11, MMP13 and MMP17 (p < 0.05)." (PMID 38786043, 2024). "The remaining genes were downregulated in all tumor groups, with the most pronounced changes observed for MMP8, MMP3, and MMP10." (PMID 38474106, 2024). "For MMP10 and NR0B1, their positive expression was only shown in tumor tissues, especially in the metastatic lymph nodes and portal vein tumor thrombus, indicating their associations with HCC metastasis." (PMID 38374122, 2024). "They further found that MMP-10, TIMP-1, and TIMP-2 were correlated to tumor size, with TIMP-2 had the most significant impact on tumor size." (PMID 35586209, 2022). "The most important observation in the research is that exosomes derived from drug-treated tumor cells contribute to a smaller increase in the expression of MMP2 and MMP10." (PMID 36012171, 2022). "Meanwhile, Mmp3, Mmp9, Mmp16 and Mmp10, which belong to the MMP family and are closely related to tumor metastasis, were downregulated." (PMID 35296801, 2022). "MMP10, 7, 13 and TIMP1 were reduced in cured mice compared to tumor bearing mice, while Krt5 and Cldn8 levels increased in cured mice." (PMID 34944584, 2021). "MMP10, MMP15 and MMP9 are found to be increased in GC and to correlate with poor patient prognosis During the metastasis process, tumour cells originating from primary tumour or metastases can be found circulating in blood, either single or in clusters." (PMID 33810350, 2021). "In the present study, we found that the expression MMP10 was remarkably inhibited by LOC101928477, which was consistent with reduced tumor growth and metastasis." (PMID 33713583, 2021). "Among the candidate list we identified (MMP10, IL1α, TIE1, FGF2, BMP6), IL1α has been reported to be released by both stromal cells and PC cells, and to promote tumor growth in PDAC." (PMID 33105540, 2020). "For example, VEGF, PLGF, MMP‐10, MMP‐3, Angpt2, and PTHLH released from tumor cells in various types of tumors are capable of triggering pulmonary endothelium hyper‐permeability, thereby accelerating extravasation of tumor cells." (PMID 33252861, 2020). "When the E:T ratio was 2:1, the expression of MMP9, MMP10 and MMP12 was also upregulated, indicating that the increase in MMP expression in the CAR-147 macrophages was related to tumour antigen stimulation." (PMID 31570753, 2019). "Knockdown of HPSE is accompanied by downregulation of MMP1, MMP7, MMP10, and MMP13, all of which are directly involved in the degradation of extracellular matrix and facilitate tumor cell invasion." (PMID 31001480, 2019). "Our results confirmed the markedly elevated expression of MMP-10 and MMP-9 in the tumor lesions of ApoE−/− mice compared to that in WT mice." (PMID 29458390, 2018).
tumor (continued). "We observed constitutively elevated levels of cytokines MCP-1, G-CSF, and RANTES in tumor cells, and of IL-1β, IL-8, MMP-1, MMP-2, and MMP-10 after co-culture." (PMID 28337194, 2017). "We also found that the interaction of tumor cells with monocytes promoted high levels of matrix metalloproteinases (MMP)-1, MMP-2, and MMP-10." (PMID 28337194, 2017). "In xenograft tumor model, the MMP-7 and MMP-10 protein expressions were diminished in MLN8237 treated group compared to DMSO by immunohistochemical staining." (PMID 25889801, 2015). "The mechanisms by which the decreased expression of MMP9 and MMP10 and the increased of TIMP4 are responsible for the depressed growth and invasion of tumor cells due to S100A4 silencing, are currently being investigated in our laboratory." (PMID 22200787, 2012). "LCM-based analysis showed the 45 kDA band to be present in both the stromal and epithelial components of the tumor microenvironment, and that MMP-3 and MMP-10 mRNA levels were higher in tumors than paired normal tissues for each compartment." (PMID 20920372, 2010). "Expression of MMP-10 was compared with that of stromelysin-1 (MMP-3) and of MT1-MMP, the expression of which has been shown to correlate with tumour invasiveness." (PMID 11237387, 2001). "Additionally, MMPs such as MMP10 and MMP13 increase vascular permeability during PMN formation, which facilitates the extravasation of circulating tumor cells." (PMID 41463352, 2025). "The results showed that, in the TCGA cohort, C12orf56 and RORC had higher expression in normal samples, while EREG, INHBB, MAGEA12, and MMP10 had higher expression in tumor samples; ASRGL1 showed no expression difference between normal and tumor samples." (PMID 39883700, 2025). "Moreover, the IHC scores of c-MET and MMP10 in CCA were highly positively correlated and significantly upregulated relative to tumor-adjacent tissues." (PMID 41048570, 2025). "Mmp10-positive TSKs more closely resembled the human TSK signature and resided at the invasive front, forming invading nests and marking invasive fronts at the tumour base." (PMID 39020166, 2024). "Histopathological examination of tumour tissue samples revealed a mixture of pigmented and non-pigmented spindle and epithelioid melanocytes, while according to immunohistochemistry, the tumours showed a strong immunopositivity for VEGF and MMP-10, and a moderate positivity for MMP-2 expression." (PMID 37104437, 2023). "In addition, metalloproteinases MMP3, MMP9, MMP10 and MMP13, known to promote tumor growth, were upregulated by CX3CL1 mediated activation of CX3CR1." (PMID 37771579, 2023). "While bulk tumor analysis represents a limitation of our study, nonetheless we identified significant upregulation of key TSK signature genes, in particular PLAU, MMP1 and MMP10, ITGA5 in MET vs. PRI- and PRI+ vs. PRI-." (PMID 35480116, 2022). "Besides, as part of the SASP, matrix metalloproteinases (MMPs) such as MMP10, MMP12, and MMP3 can lead to cleavage of NKG2D ligands on the surface of senescent tumor cells that allows them to evade NK cell surveillance." (PMID 36330438, 2022). "The authors concluded that MMP-10 may have a role in the different invasive patterns observed in BCC and SCC, contributing to the tumor aggressive behavior." (PMID 34204372, 2021). "The expression levels of MMP7 (P = 0.0123) and MMP13 (P = 0.0147) were significantly increased in the metastatic tumour samples, while that of MMP10 (P = 0.0932) was not." (PMID 31996191, 2020). "MMP-10 contributes to HCC development, participating in tumor angiogenesis, growth, and lung dissemination, induced by hypoxia, an increased CXCR4 expression, stromal-derived factor-1, and increased C-Jun transcriptional activity, resulting in the EMT of HCC cells." (PMID 31886121, 2019).